MIR29B2CHG (MIR29B2 and MIR29C host gene)
Synonyms: FLJ35650; formerly C1orf132
Gene: Long non-coding RNA gene on chromosome 1 (207,760,650 to 207,879,121, reverse strand). Ensembl gene ENSG00000203709.
Gene Ontology:
Biological process: miRNA-mediated post-transcriptional gene silencing
Cellular component: RISC complex
Diseases named in the same sentence as MIR29B2CHG in open-access papers:
MIR29B2CHG is named in the same sentence as 7 diseases in open-access papers, as found by Europe PMC text mining. Sharing a sentence is not in itself a finding about the gene and the disease.
MIR29B2CHG shares sentences with these, for which no sentence is quoted: cancer (3 papers); breast carcinoma (2); tumor (2); Graves disease (1); Infertility (1); lung carcinoma (1); triple-negative breast carcinoma (1).